SELENOP (selenoprotein P)
Description:
Might be responsible for some of the extracellular antioxidant defense properties of selenium or might be involved in the transport of selenium. May supply selenium to tissues such as brain and testis.
Synonyms: SeP; SELP; SEPP1; SEPP
Tractability: Antibody: UniProt places it where antibodies can reach, with high confidence; its Gene Ontology location is reachable by antibodies, with high confidence; UniProt predicts a signal peptide or a membrane-spanning region.
Gene: Protein-coding gene on chromosome 5 (42,799,880 to 42,887,392, reverse strand). Ensembl gene ENSG00000250722.
Subcellular location: Secreted
Subcellular location (Human Protein Atlas): Golgi apparatus; Nucleoplasm; Connecting piece; Predicted to be secreted
Pathways (Reactome):
Hemostasis: Platelet degranulation
Gene Ontology:
Molecular function: selenium binding
Biological process: response to oxidative stress; response to selenium ion
Cellular component: extracellular exosome; extracellular region; platelet dense granule lumen
Genetic constraint (gnomAD): Loss-of-function variants: 16 observed, 19.95 expected, observed/expected ratio (o/e) 0.8, 90% interval 0.54 to 1.22. The upper end of that interval is the gene's LOEUF score, 1.22, which puts it in group 5 of 6, group 1 being the genes least tolerant of losing a copy. Missense variants: 265 observed, 284.95 expected, observed/expected ratio (o/e) 0.93, 90% interval 0.84 to 1.03. Synonymous variants: 79 observed, 89.34 expected, observed/expected ratio (o/e) 0.88, 90% interval 0.74 to 1.07.
Homologues: Orthologues: rat Selenop (72% identical), mouse Selenop (71% identical), dog SELENOP (41% identical), guinea pig Selenop (33% identical), tropical clawed frog selenop1 (32% identical).
Diseases named in the same sentence as SELENOP in open-access papers:
SELENOP is named in the same sentence as 172 diseases in open-access papers, as found by Europe PMC text mining. Sharing a sentence is not in itself a finding about the gene and the disease. The quoted sentences say what the papers report.
Insulin resistance (42 papers, 2012 to 2025). Increased resistance towards insulin, that is, diminished effectiveness of insulin in reducing blood glucose levels. "SELENOP is a well-known hepatokine to cause insulin resistance, which reduces phosphorylated AKT in liver and muscle, and decreases the number of pancreas β cells and GSIS." (PMID 40760121, 2025). "It is worth noting that insulin resistance (5.5) has the greatest emergent strength, followed by cell-derived chemotaxin 2 (2.7), selenoprotein p (2.67), and risk (2.56)." (PMID 38881894, 2024). "A serial analysis of gene expressions revealed that SELENOP is associated with insulin resistance in humans." (PMID 37895024, 2023). "Insulin sensitivity in the liver and skeletal muscle was improved in SELENOP-deficient mice, while intraperitoneal injection with SELENOP impaired insulin signaling, suggesting that SELENOP is a hepatokine capable of inducing insulin resistance." (PMID 37895024, 2023). "Selenoprotein P (SeP) is a secretory protein primary produced in the liver that causes insulin resistance in humans, and its serum levels have been found to be significantly elevated in NAFLD patients compared to healthy controls." (PMID 36010588, 2022). "High-plasma Se and SELENOP levels are associated with insulin resistance and NAFLD, the SELENOP level was positively correlated with insulin resistance and NAFLD, but for serum Se, the conclusions were different." (PMID 35624837, 2022). "Decrease in SELENOP causes various dysfunctions related to Se deficiency and oxidative stress, while excessive SELENOP causes insulin resistance." (PMID 34124127, 2021). "In this regard, SELENOP levels are elevated in T2D patients, and excessive SELENOP causes insulin resistance and also impairs the function of pancreatic β-cells, suggesting excessive SELENOP as a promising therapeutic target in T2D patients." (PMID 34445217, 2021). "Selenoprotein P (SeP) is a glycoprotein that can be released by liver and adipose tissue and has been shown to contribute to insulin resistance associated with NAFLD." (PMID 33198247, 2020). "For example, expression of a couple of selenoproteins, including Gpx1, selenoprotein P and selenoprotein M, is associated with insulin resistance and/or obesity." (PMID 27653523, 2017). "Additionally, selenium’s impact on selenoprotein P has been associated with hepatic gluconeogenesis and insulin resistance." (PMID 40182029, 2025). "Indeed, elevated serum selenoprotein-P (encoded by Sepp1) has been associated with obesity and diabetes in humans, and overexpression both in vitro and in vivo leads to insulin resistance." (PMID 31176677, 2019). "Experimental studies have demonstrated that SELENOP affects the phosphorylation of key molecules in the insulin signaling pathway, thereby impairing insulin signaling and leading to insulin resistance in hepatocytes and myocytes." (PMID 39149550, 2024). "Studies found that the SELENOP levels were positively correlated with insulin resistance and NAFLD, but for serum selenium levels, the conclusions were different." (PMID 37895024, 2023). "Collectively, most of the studies on the role of selenoprotein P in the progression of insulin resistance and type 2 diabetes strongly support its potential as a novel therapeutic target in various metabolic disorders." (PMID 34944728, 2021). "A decrease in SELENOP causes deficiency in selenoproteins and various dysfunctions with oxidative stress, while excess SELENOP induces insulin resistance, which can lead to type 2 diabetes." (PMID 34124127, 2021). "Several molecules have been reported as hepatokines and adipokines involved in insulin resistance, such as selenoprotein P and adiponectin, respectively." (PMID 33005239, 2020). "HCV was also reported to induce selenoprotein P (SeP), an hepatokine involved in insulin resistance and type 2 diabetes." (PMID 32183176, 2020).
Insulin resistance (continued). "Excessive levels of selenoprotein P (SeP) have been shown in humans with metabolic diseases and are positively correlated with insulin resistance, which is consistent with its insulin-desensitizing effects observed in animal and in vitro models." (PMID 32604889, 2020). "Selenoprotein P is one of the hepatokines synthesized and secreted from hepatocytes that has been established to induce insulin resistance." (PMID 31455007, 2019). "They concluded that IH stress upregulates the levels of selenoprotein P in human hepatocytes to accelerate insulin resistance." (PMID 31455007, 2019). "In mice, the administration of selenoprotein P induced hepatic and peripheral insulin resistance, whereas both genetic deletion and RNA interference-mediated knockdown of selenoprotein P ameliorated insulin signaling and improved glucose tolerance." (PMID 31736870, 2019). "This suggests that hepatic overproduction of SELENOP coexists with systemic insulin resistance in type 2 diabetic condition." (PMID 30425271, 2018). "We have rediscovered selenoprotein P (SELENOP) as a hepatokine that induces insulin resistance and hyperglycemia in mice." (PMID 30425271, 2018). "The liver secretory selenoprotein SELENOP is related to insulin resistance." (PMID 37895024, 2023). "SELENOP binds heparin and participates in insulin resistance." (PMID 37238669, 2023). "Nevertheless, excessive SELENOP may lead to insulin resistance, and treatment with the full-length form of SELENOP may impair insulin signal transduction in cultured hepatocytes." (PMID 35883754, 2022). "Selenoprotein P is a glycoprotein primarily secreted by the liver, and its expression is increased in humans with NAFLD, type 2 diabetes, and cardiovascular diseases, in close association with insulin resistance and hyperlipidemia." (PMID 34944728, 2021). "Under this hypothesis, the primary cause of the association between selenium and diabetes is the presence of insulin resistance that raises the synthesis of SELENOP, the main selenium transporter." (PMID 34262926, 2021). "For example, selenoprotein P, a type of hepatokines, is correlated positively with insulin resistance and could be a therapeutic target for type 2 DM." (PMID 31557884, 2019). "The potential mechanism to link Se to insulin resistance and obesity may be partly mediated by glutathione peroxidase and selenoprotein P, due to their notable anti-inflammation functions." (PMID 30813489, 2019). "Similarly, selenoprotein P (SELENOP), a hepatogenic secreted protein, may induce insulin resistance by inhibiting adenosine monophosphate-activated protein kinase." (PMID 40416378, 2025). "Likewise, in vivo administration of selenoprotein P led to hepatic and peripheral insulin resistance, while liver-specific genetic ablation significantly ameliorated systemic glucose intolerance in association with enhanced insulin signaling in the liver and skeletal muscle." (PMID 34944728, 2021). "Taking a different perspective, Schomburg hypothesized that rather than high selenium being a cause for insulin resistance, diabetes potentially causes increased synthesis of SELENOP by the liver, which leads to increased circulating selenium." (PMID 34262926, 2021). "Taken together with these early reports, the current findings raise the possibility that pharmacological or lifestyle interventions against increased circulating levels of SELENOP could improve glucose metabolism by attenuating systemic insulin resistance in humans." (PMID 30425271, 2018). "In humans, selenoprotein P is increased in patients with T2D and NAFLD, and is positively correlated with triglycerides, glucose, and insulin resistance." (PMID 31736870, 2019). "The role for SELENOP in the regulation of glucose metabolism was formerly unknown, but SELENOP has thereafter emerged from human liver screening for secretory proteins whose hepatic gene expression levels are positively correlated with the severity of insulin resistance." (PMID 30425271, 2018).
Insulin resistance (continued). "Additionally, EGCG-derived autoxidation products help improve insulin sensitivity by reducing liver-derived secretory selenoprotein P (SELENOP), a protein involved in insulin resistance." (PMID 39942757, 2025). "We aimed to test the hypothesis that selenoprotein P (SELENOP), a hepatokine involved in the development of both insulin resistance and impaired insulin production in mice, is related to future onset of hyperglycemia in humans." (PMID 30425271, 2018). "Selenoprotein P hepatic transcription is regulated similarly to that of a gluconeogenic enzyme through transcription factors FoxO1 and HNF-4α together with the co-activator PGC-1α and may also become dysregulated in hyperglycemia and insulin-resistance states." (PMID 37895024, 2023).
diabetes (23 papers, 2012 to 2026). "It has been shown that increased plasma SELENOP levels are associated with hyperglycemia in patients with type 2 diabetes mellitus (T2DM)." (PMID 37895024, 2023). "It is worth emphasizing that selenoprotein P has been proposed as a diabetes-associated hepatokine involved in impaired angiogenesis via the induction of VEGF (vascular endothelial growth factor) resistance in vascular endothelial cells." (PMID 32605214, 2020). "Elevated SELENOP levels, linked to both cancer progression and diabetes, may promote tumor growth by modulating inflammation and oxidative stress." (PMID 41244925, 2025). "Selenoprotein P (SelP), a selenium-supply protein, is hypothesized to raise the risk of diabetes by promoting insulin resistance and dysregulating glucose metabolism." (PMID 37275636, 2023). "Interestingly, in humans, high serum selenium and selenoprotein P levels are associated with diabetes biomarkers, which is in concordance with animal data." (PMID 37107221, 2023). "The cross-sectional associations between plasma Se, selenoprotein P and diabetes risk could be explained by the linked expression of selenoprotein P and gluconeogenic enzymes that promote the de novo biosynthesis of glucose." (PMID 23028897, 2012). "In our model, we identified five differentially expressed diabetes-related genes, with GSN and PGR exhibiting heightened expression levels in the low-risk group, whereas CDKN2A, SELENOP, and TRPC1 demonstrated increased expression in the high-risk group." (PMID 41244925, 2025). "This revealed an enrichment for proteins involved in response to oxidative stress and cellular oxidant detoxification, such as glutathione peroxidase 7 (GPX7) and selenoprotein P (SEPP1), in line with oxidative stress being a feature of diabetes." (PMID 40829182, 2025). "Regarding glucose tolerance in muscles, adenosine monophosphate-activated protein kinase (AMPK) is a mediator in the regulatory activity of SELENOP, so this fact considers SELENOP a future therapeutic target in diabetes mellitus 2 types." (PMID 37895024, 2023). "Selenium and selenoprotein P also exert beneficial or adverse health effects on the development of diabetes and cardiovascular diseases depending on their concentrations and circumstances." (PMID 33693023, 2021). "Another selenoprotein potentially important in the etiology of diabetes is selenoprotein P (Sepp1) which is produced mainly in the liver and secreted into plasma, acting as a Se transporter, and having also antioxidant properties." (PMID 27983572, 2016). "In this study, we aimed to investigate the prospective associations between serum levels of pre-diagnosis TEs and their functional biomarkers (Selenoprotein P (SelenoP) and Free Zinc (Free Zn)) with diabetes-related vascular complications in the EPIC-Potsdam cohort." (PMID 40707897, 2025). "It has been shown that therapeutic drugs used for diabetes, such as metformin and exendin-4, can suppress SELENOP expression in the liver; however, the targets of these reagents include a wide range of genes and proteins and their specificity for SELENOP is low." (PMID 34142161, 2021). "An experimental animal model of diabetes revealed that neutralization of SELENOP improved glucose tolerance and insulin secretion, suggesting that this selenoprotein may play a particularly important role in the pathogenesis of T2DM." (PMID 34262926, 2021). "The association between diabetes and Se may be due to higher levels of Se transport protein selenoprotein P and not necessarily to higher Se exposure." (PMID 33670707, 2021). "Thus significant correlations have been found between serum selenoprotein P and adiponectin, fasting plasma glucose and HbA1c while circulating selenoprotein P concentration was significantly higher in people with type-2 diabetes or pre-diabetes than in those with normal glucose tolerance." (PMID 23028897, 2012).
diabetes (continued). "To further validate the protein expression levels of the five key diabetes-related genes (CDKN2A, GSN, PGR, SELENOP, and TRPC1) identified in our prognostic model, we utilized IHC staining data from the HPA database." (PMID 41244925, 2025). "In this context, the study focusing on the relationship between selenoproteins and diabetes has received considerable attention, indicating unsuspected key roles of SELENOP and GPX1 in diabetes." (PMID 34445217, 2021). "Furthermore, stratification of UCEC patients by diabetic status revealed that the dysregulation of SELENOP, CDKN2A, and PGR was specifically exacerbated by diabetes." (PMID 41244925, 2025). "Our analysis revealed a distinct stratification: while TRPC1, SELENOP, CDKN2A, GSN, and PGR all showed significant dysregulation in UCEC tissues compared to normal endometrium, only SELENOP, CDKN2A, and PGR exhibited diabetes-specific modifications in UCEC patients." (PMID 41244925, 2025). "The trace element concentrations were not significantly different in relation to diabetes, chronic cardiac disease or obesity, but tumour patients presented with significant deficits in Zn and SELENOP." (PMID 34684306, 2021). "In addition, given that the role of SELENOT in diabetes seems to be somewhat similar to that of SELENOP, whether and how SELENOT and SELENOP interact with each other is an interesting topic." (PMID 34445217, 2021).
type 2 diabetes (23 papers, 2012 to 2026). "Elevated levels of SELENOP are associated with decreased insulin sensitivity and an increased risk of type 2 diabetes." (PMID 39149550, 2024). "We have re-discovered selenoprotein P as a hepatokine that causes multi-signal resistances leading to type 2 diabetes, such as insulin resistance, angiogenesis resistance, ischemia-reperfusion injury, insulin secretory failure, and exercise resistance." (PMID 33693023, 2021). "Plasma adiponectin concentration, a recognised independent predictor of type-2 diabetes risk and known to be correlated with circulating selenoprotein P, was the biomarker chosen." (PMID 23028897, 2012). "Sulforaphane, a plant secondary metabolite found in crucifers, decreases selenoprotein P levels by enhancing lysosomal degradation, suggesting that this phytochemical is a candidate for controlling selenoprotein P-associated diseases like type 2 diabetes." (PMID 37857700, 2023). "However, selenoproteins are generally considered beneficial for health, although GPx1 is implicated in insulin resistance (IR) and SELENOP is associated with type 2 diabetes mellitus (T2DM)." (PMID 34207090, 2021). "An increase in selenoprotein P was found in humans with diabetes type 2, MASLD, and cardiovascular diseases." (PMID 37998747, 2023). "In a mouse model of diabetes type 2, the administration of antibodies against selenoprotein P improved glucose tolerance and insulin secretion." (PMID 37998747, 2023). "Several selenoproteins including glutathione peroxidases, selenoprotein P and selenoprotein S are known to play roles in the regulation of type 2 diabetes." (PMID 36438755, 2022). "Serum levels of selenoprotein P are elevated during aging, and in people with type 2 diabetes, non-alcoholic fatty liver disease, and chronic hepatitis C." (PMID 33693023, 2021). "In line with this notion, hepatic selenoprotein P expression is upregulated in animal models of diet-induced obesity and type 2 diabetes." (PMID 34944728, 2021). "On the other hand, recent studies indicate that excess selenoprotein P exacerbates glucose metabolism and promotes type 2 diabetes." (PMID 32001950, 2020). "Selenoprotein P is secreted by the liver and when present in excess it promotes development of type 2 diabetes." (PMID 29162828, 2017). "To date, apart from the findings in the top tertile of the NPC trial, which derive from a post-hoc analysis of a small trial, all the evidence linking Se or selenoprotein P to type-2 diabetes is cross-sectional." (PMID 23028897, 2012). "This interpretation is consistent with the observed inhibition of SELENOP uptake into renal HEK293 target cells by antibodies to SELENOP, nicely echoing published results on SELENOP-neutralizing antibodies antagonizing Se uptake as novel candidates for type 2 diabetes therapy." (PMID 34884891, 2021). "However, the increase in SELENOP in the case of type 2 diabetes enhances the uptake of SELENOP via LRP1, which is related to the increase in insulin and exercise resistance." (PMID 34124127, 2021). "Additional clinical studies on a larger number of samples are required to assess whether elevation of circulating SELENOP is involved in the development of type 2 diabetes." (PMID 30425271, 2018). "Because insulin exerts the inhibitory effects on gene expression for SELENOP in the hepatocytes, impaired insulin action in fatty liver or type 2 diabetes may up-regulate SELENOP production in the liver." (PMID 30425271, 2018). "Another possible reason for a lack of effect of Se supplementation on adiponectin (PRECISE) or type-2 diabetes (SELECT) is that Se or selenoprotein P does not cause an increased risk of type-2 diabetes or a fall in circulating adiponectin." (PMID 23028897, 2012).